ALB (albumin)
Diseases named in the same sentence as ALB in open-access papers (continued):
Sharing a sentence is not in itself a finding about the gene and the disease.
bacteremia (continued). "Bacterial surface proteins, such as glycosyltransferase, the sialic acid-binding human serum albumin (Hsa), and the co-aggregation proteins CshA and CshB, play a key role in host endothelial cell invasion and bacteremia development." (PMID 36466857, 2022). "A previous study reported that a sharp drop in the serum albumin level due to bacteremia seriously affected the prognosis." (PMID 36067189, 2022). "In contrast, there were significant differences in bacteremia rate, iMELD score, creatinine, serum sodium, and albumin among the three types of SBP." (PMID 36611386, 2022). "Survival group patients had a significantly lower Charlson comorbidity index, Pitt bacteremia score, and albumin levels." (PMID 34209780, 2021). "For each 0.1 g/dL decrease in serum albumin level, the odds ratio (95% confidence intervals) of mortality in the period of 0–30 days after bacteremia was 0.86 (0.84–0.88)." (PMID 33925831, 2021). "According to the multivariate logistic regression analysis, higher MIC of rifampin, increased SAPS II, and elevated CRP/albumin ratio on the day of bacteremia were significantly related to mortality." (PMID 32408478, 2020). "Variables associated with overall mortality in the univariate analysis were hospital-acquired bacteremia, polymicrobial bacteremia, failure to perform surgical debridement of the ulcer, and serum albumin below 23 g/L." (PMID 29479635, 2018). "Independent risk factors for mortality were hospital-acquired bacteremia, polymicrobial bacteremia, and serum albumin below 23 g/L." (PMID 29479635, 2018). "Low serum albumin and elevated procalcitonin, consistent with bacterial sepsis, were observed in >70% of cases." (PMID 28726607, 2017). "Serum albumin was <3.5 g/dL in 73 (81%) of 90 cases, and serum procalcitonin was >0.5 ng/mL in 10 (71%) of 14 cases, both findings consistent with bacterial sepsis." (PMID 28726607, 2017). "Our results are consistent with those studies, and the combination of high CRP and low albumin levels appears to readily predict the prognosis of S. maltophilia bacteremia." (PMID 28938875, 2017). "Analysis of serum albumin levels after bacteremia and infection serum albumin levels showed an acute decrease as a result of infection, again correlating with poor prognosis." (PMID 28869492, 2017). "Lower albumin concentrations, VAP status, worsening infections, or complications with baseline bacteremia have been associated with poor clinical outcomes." (PMID 28044137, 2016). "The cats in group A exhibited a significant increase in total serum protein and globulin and a decrease in albumin particularly at 3 to 8 weeks after M. haemofelis exposure, consistent with maximal bacteremia in these cats." (PMID 26403079, 2015). "Most of the 42 patients with HD CRB were elderly, exhibited low levels of serum albumin and hemoglobin at the onset of bacteremia, and had a history of prolonged hospitalization." (PMID 22947300, 2012). "Furthermore, markers of disease severity, including serum albumin and renal function parameters, were more profoundly altered in patients with bacterial sepsis." (PMID 40722789, 2025). "In addition, in the low-intensity group, P. gingivalis bacteremia also significantly increased Albumin deposition in the hippocampal tissues, while had little effect on that in the cortex tissues and Evans blue dye deposition." (PMID 36631446, 2023). "These risk factors included septic shock, Pitt bacteremia scores ≥ 4, PCT ≥ 10 ng/mL, positive BG, serum albumin levels <30.0 g/L, time from fever to antifungal treatment initiation ≥5 days and time between neutropenia and antifungal treatment ≥10 days (p < 0.05)." (PMID 37520379, 2023). "Interestingly, elevation of serum sPLA2 was accompanied by a decrease in serum albumin interactions with cell membranes as well as decreased activity of a specific fraction of albumin (SFA) in patients with bacterial sepsis." (PMID 36232977, 2022).
bacteremia (continued). "In that study, the latest albumin measurement was taken 8–30 days before the date of bacteremia in 422 patients, and a higher proportion of patients died within 30 days if the albumin level decreased between days 8–30 prior to bacteremia and the eventual date bacteremia was identified." (PMID 33925831, 2021). "The risk factors independently associated with mortality were hospital-acquired bacteremia (odds ratio [OR] 5.51, 95% confidence interval [95%CI] 1.24–24.40), polymicrobial bacteremia (OR 6.88, 95%CI 1.22–38.89), and serum albumin <23 g/L (OR 8.00, 95%CI 1.73–37.01)." (PMID 29479635, 2018). "The low serum albumin is also consistent with bacterial sepsis." (PMID 28726607, 2017). "Serum phosphate levels correlated positively, and fever, bacteremia, hospital stay and weight loss negatively, with mean serum albumin but did not negate the effect of nPCR." (PMID 24499139, 2013). "Prospective study may be needed to clarify the effects of albumin in critical bacteremia children." (PMID 32907533, 2020). "The association between MTB bacteremia and 30-day mortality was similar after adjustment for confounders (CD4 count, absence of HAART, anti-tuberculosis therapy prior to hospitalization and serum albumin concentration) (adjusted HR 1.8, 95% CI 1.2–2.8, p = 0.003)." (PMID 23940557, 2013). "We found that in the high-intensity group, P. gingivalis bacteremia significantly enhanced BBB permeability so that the deposition of Evans blue dye and Albumin, a neurotoxic substance, significantly increased in the rat brain hippocampal and cortex tissues." (PMID 36631446, 2023). "One more limitation is that the study population was relatively severe according to the high prevalence of resistant strains, low albumin level, high SOFA scores, and high incidence of bacteremia." (PMID 31635200, 2019). "Patients with CPKP also had lower albumin concentrations and higher APACHE II and Pitt bacteremia scores, and they were more likely to have received corticosteroid therapy or to have been exposed to antimicrobial therapy in the previous 14 days." (PMID 30810470, 2019). "In the three bitches with positive blood cultures (bacteremia), the concentrations of CRP were 97, 272 and 298 mg/L, concentrations of SAA were 56.6, 114.7 and 117.9 mg/L and concentrations of albumin 21, 26 and 20 g/L." (PMID 25430894, 2014). "Patients in the bacteremia group had significantly lower levels of hemoglobin, red blood cell count, cholesterol, and albumin compared to those in the non-bacteremia group (all p < 0.01)." (PMID 40792110, 2025). "As shown in patients during the initial phase of bacteremia, after an initial increase in CRP, levels drop over several days, whereas after the sudden drop of serum albumin levels due to trans-capillary leakage, serum levels remain low for a much longer period." (PMID 33925831, 2021). "This notion is further supported by our finding that the α7 KO mice with direct inoculation of E. coli K1 into the CSF show reduced bacteremia and CNS inflammatory response (e.g., decreased PMN recruitment and albumin leakage into CSF) when compared to that in the wildtype animals (data not shown)." (PMID 21966399, 2011). "Since the use of the qPitt bacteremia score in Gram-negative BSI is limited and its relationship with CRP/albumin ratio in patients with BSI is largely unexamined, we sought to explore this further." (PMID 39252713, 2024).
rheumatoid arthritis (59 papers, 2005 to 2026). A chronic, systemic autoimmune disorder characterized by inflammation in the synovial membranes and articular surfaces. "Changes in albumin concentrations in the synovial fluid are often associated with inflammatory conditions such as OA or rheumatoid arthritis, with levels typically decreasing, rendering it a potential biomarker in clinical settings." (PMID 38672430, 2024). "This aligns with prior research indicating that the controlled nutritional status score (CONUT) and the nutritional risk index (NRI), which include nutritional markers such as albumin, body weight, and lymphocyte count, are associated with increased all-cause mortality in rheumatoid arthritis." (PMID 37284646, 2023). "We aimed to assess hepatic proteins in rheumatoid arthritis patient’s: inflammation markers (high-sensitive C-reactive protein (CRPhs), haptoglobin (Hp)), and those implicated in iron metabolism (ferritin, Albumin (Alb), Cp, α-1-acid glycoprotein (AAG) and Tf) and MPO." (PMID 28894708, 2017). "Additionally, it was demonstrated that the utilization of both albumin and dNLR in conjunction may yield superior results in terms of diagnostic efficacy for rheumatoid arthritis." (PMID 38041687, 2024). "As shown in several studies, patients with rheumatoid arthritis, whose albumin levels fluctuate greatly depending on a disease activity, present variable free fraction of naproxen." (PMID 40051558, 2025). "A previous study has shown that patients with rheumatoid arthritis have lower albumin levels compared to healthy individuals." (PMID 38792397, 2024). "Despite cancer, several diseases like rheumatoid arthritis, haemorrhage, and ischaemia use albumin as a biomarker." (PMID 39816318, 2024). "The importance of citrullinated albumin for rheumatoid arthritis has also been reported by Astrid Tutturen." (PMID 35225987, 2022). "Albumin-based drug delivery is also applicable in other conditions such as rheumatoid arthritis in which inflammatory environments of joints attract more albumin." (PMID 36365125, 2022). "Possibly, this accumulation of albumin can even promote the targeting of inflamed tissues by Anticalin-ABD:albumin complexes as already demonstrated for albumin-based delivery of drugs in a mouse model of rheumatoid arthritis." (PMID 34759826, 2021). "Considering the oxidative changes in serum proteins, particularly albumin, and serum antioxidants in rheumatoid arthritis it is possible that the extension of these changes reflects different activities of the disease." (PMID 26835218, 2016). "In rheumatoid arthritis, the serum albumin thiol is more oxidized in arthritic patients than in healthy volunteers and the serum albumin levels fall in proportion to the severity of the disease." (PMID 26835218, 2016). "The association between the neutrophil percentage to albumin ratio (NPAR) and the risk of osteoarthritis (OA) and rheumatoid arthritis (RA) remains unclear." (PMID 39917306, 2025). "This approach demonstrated superior efficacy over corticosteroids and small-molecule MMP inhibitors, highlighting the therapeutic promise of albumin ‘hitchhiking’ for targeted, systemic delivery of gene-silencing therapeutics to treat osteoarthritis and rheumatoid arthritis." (PMID 40379798, 2025). "Furthermore, the synovial membrane that separates SF from plasma allows small globular proteins (albumin and globulins) to freely interchange between blood and SF, and this process is more intense in rheumatoid arthritis." (PMID 38398051, 2024). "Moreover, we applied our system to produce ozoralizumab, a multispecific VHH that binds to human TNF-α and albumin and are marketed as a rheumatoid arthritis drug." (PMID 39161731, 2024). "After feature selection, 9 variables were identified: age, rheumatoid arthritis, lung diffusing capacity for carbon monoxide, right ventricular diameter, right atrial area, honeycombing, immunosuppressive agents, aspartate transaminase and albumin." (PMID 34996461, 2022).
rheumatoid arthritis (continued). "To address this issue, we have used a collection of single and compound Vav family knockout mice in experimental models for antigen-dependent (methylated bovine serum albumin injections) and neutrophil-dependent (Zymosan A injections) rheumatoid arthritis in mice." (PMID 34205377, 2021). "Albumin has been widely employed as macromolecular carrier for drug delivery purpose to extend the plasma half-life of therapeutic molecules and has been shown to selectively accumulate and to be metabolized in the inflamed joints of patients with rheumatoid arthritis." (PMID 23006786, 2012). "Heat-induced denaturation of bovine serum albumin results in the expression of antigens linked to Type III hypersensitivity reaction, which may be indicative of conditions including systemic lupus erythematosus, glomerulonephritis, rheumatoid arthritis, and serum sickness." (PMID 40722802, 2025). "With the development and synthesis of functional nanomaterials, serum albumin, such as human serum albumin (HSA), has become a popular material used in the cure of rheumatoid arthritis." (PMID 37577749, 2023). "Covering both fibrinogen and albumin, FAR reflected systemic inflammation in patients with rheumatoid arthritis, which was comparable to C-reactive protein." (PMID 32879878, 2020). "Ozoralizumab, a bispecific therapy in active Phase-III clinical trials for rheumatoid arthritis, has a VH(TNFA)–VH(ALB)–VH(TNFA) configuration, where VH(TNFA) is a heavy chain designed to bind to TNF-α, and VH(ALB) is another heavy chain designed to bind ALB." (PMID 31555805, 2020). "The findings reported herein indicate that the fusion protein is likely to be an ideal biological agent in the treatment of rheumatoid arthritis, and that genetic fusion of small protein drugs to albumin is a promising drug delivery approach for RA targeted therapy." (PMID 23006786, 2012). "Wild-type mice, CA1-Tg treated with bovine serum albumin (BSA) and transgenic mice over-expressing PADI4 (PADI4-Tg), a gene known to be involved in rheumatoid arthritis, were used as controls." (PMID 23256642, 2012). "During the early stage of renal involvement in rheumatoid arthritis, no clinical abnormally levels are detected on creatinine, urea nitrogen, and 24-hour urinary albumin." (PMID 39364405, 2024). "The neutrophil percentage‐to‐albumin ratio (NPAR), is a multidimensional health assessment index composed of inflammatory markers (neutrophils) and nutritional markers (albumin) to reflect inflammation and nutritional status, has shown unique potential in rheumatoid arthritis (RA) research." (PMID 41551209, 2026). "Rheumatoid arthritis patients have a low level of albumin that is not related to disease activity." (PMID 33777988, 2021). "The fibrinogen-to-albumin ratio (FAR) has emerged as a promising inflammatory marker, but its relationship with rheumatoid arthritis (RA) disease activity remains unclear." (PMID 41341588, 2025). "The relationship between the C-reactive protein (CRP)-albumin-lymphocyte (CALLY) index and disease activity of rheumatoid arthritis (RA) has not been explored at present." (PMID 41640573, 2026).
hyperuricemia (58 papers, 2015 to 2026). An abnormally high level of uric acid. "However, PNI level was not related to all-cause mortality in females, those with a BMI <30 kg/m2, DM, hyperuricemia or albumin <35 g/L, and current smokers with CKD after adjustment for multiple confounders." (PMID 38156280, 2023). "Hence, using the Taiwan Biobank dataset, we aimed to explore the capability of liver function parameters, including gamma-glutamyl transferase, total bilirubin, albumin, alanine aminotransferase and aspartate aminotransferase in association with the subsequent development of hyperuricemia." (PMID 36364933, 2022). "Furthermore, a positive association was found between hyperuricemia and albumin levels >3.5 g/dL." (PMID 32867018, 2020). "Male participants showed higher rates of hyperuricemia, elevated cystatin C levels, and increased albumin-to-creatinine ratios." (PMID 41200622, 2025). "Hyperuricemia and elevated cystatin C levels and albumin-to-creatinine ratio were significantly more common in male participants as compared to female participants (p = 0.033-0.003)." (PMID 41200622, 2025). "This post hoc analysis of a phase 3 clinical trial of oral administration of dotinurad to patients with hyperuricemia investigated the effects on urinary albumin levels at 34 and 58 weeks in a subset of patients with microalbuminuria." (PMID 40839334, 2025). "In the derivation cohort, univariate analysis demonstrated that age, hyperuricemia, serum albumin, proteinuria, eGFR, and sPLA2R-ab were significantly correlated with renal progression in PMN patients." (PMID 38818472, 2024). "Consistent with previous findings, our multivariate Cox analysis revealed that older age, hyperuricemia, lower serum albumin, heavier proteinuria, and lower eGFR were independently associated with renal progression in PMN patients." (PMID 38818472, 2024). "The RVL group was significantly younger; had a shorter course of disease; had more severe proteinuria, hematuria, and hyperuricemia; and had lower levels of serum albumin, hemoglobin, and eGFR (all p < 0.05)." (PMID 34711199, 2021). "In our present study, even after adjustment for nutrition and inflammation factors such as serum albumin, CRP, concentrations of creatinine, phosphorus and body mass index, hyperuricemia was still an independent predictor of all‐cause mortality." (PMID 34309202, 2021). "Concerning frequent adverse drug reactions, diarrhea or digestive tract reactions were reported in three studies, decreased albumin levels were reported in one study, and hyperuricemia was reported in one study." (PMID 34044777, 2021). "On the other hand, l‐Carnitine treatment to either states of hyperuricemia significantly elevated plasma albumin level when each treated group was compared to its respective untreated group (p < .001 in each one)." (PMID 31782919, 2019). "Furthermore, hypertriglyceridemia, hyperuricemia, elevated cystatin C levels, and urine albumin to creatinine ratio were significantly more common in male participants." (PMID 41200622, 2025). "The evidence that dotinurad lowers urinary albumin in this population is of interest, given the possibility that dotinurad may have a urinary albumin-lowering effect in patients with microalbuminuria and hyperuricemia." (PMID 40839334, 2025). "This post hoc analysis of a Japanese, multicenter, phase 3 clinical trial (ClinicalTrials.gov identifier, NCT03006445) of dotinurad in patients with hyperuricemia investigated the effects on urinary albumin levels among a subset of patients with microalbuminuria." (PMID 40839334, 2025). "Additionally, serum albumin and hyperuricemia have been identified as indicators of disease severity and the risk for renal deterioration in PMN patients." (PMID 38818472, 2024). "However, the albumin (ALB) level (p < 0.001), glycated albumin level (a marker of glycemic control) (p = 0.044) and creatinine level (p < 0.001) in hyperuricemia patients were significantly higher than that of normal SU patients." (PMID 39618812, 2024).